DDAH1 (dimethylarginine dimethylaminohydrolase 1)
Description:
Hydrolyzes N(G),N(G)-dimethyl-L-arginine (ADMA) and N(G)- monomethyl-L-arginine (MMA) which act as inhibitors of NOS. Has therefore a role in the regulation of nitric oxide generation.
Synonyms: DDAH-1; DDAH; DDAHI; HEL-S-16
Tractability: Small molecule: a structure with a bound ligand is known; a high-quality ligand is known; it has a high-quality binding pocket. Antibody: the Human Protein Atlas places it where antibodies can reach. PROTAC: ubiquitination databases record sites on it; its protein half-life has been measured; a small molecule that binds it is known.
Target class: Enzyme; Hydrolase
Gene: Protein-coding gene on chromosome 1 (85,318,481 to 85,578,363, reverse strand). Ensembl gene ENSG00000153904.
Subcellular location (Human Protein Atlas): Cytosol; Plasma membrane; Nucleoli
Pathways (Reactome):
Metabolism: eNOS activation
Gene Ontology:
Molecular function: dimethylargininase activity; nitric-oxide synthase inhibitor activity; amino acid binding
Biological process: L-arginine catabolic process; negative regulation of cell population proliferation; negative regulation of cellular response to hypoxia; negative regulation of vascular permeability; arginine metabolic process; nitric oxide metabolic process; positive regulation of nitric oxide biosynthetic process; regulation of systemic arterial blood pressure; positive regulation of angiogenesis; positive regulation of nitric oxide-cGMP mediated signal transduction
Cellular component: extracellular exosome; cytosol
Genetic constraint (gnomAD): Loss-of-function variants: 13 observed, 18.18 expected, observed/expected ratio (o/e) 0.72, 90% interval 0.47 to 1.14. The upper end of that interval is the gene's LOEUF score, 1.14, which puts it in group 4 of 6, group 1 being the genes least tolerant of losing a copy. Missense variants: 298 observed, 285.91 expected, observed/expected ratio (o/e) 1.04, 90% interval 0.95 to 1.15. Synonymous variants: 140 observed, 117.96 expected, observed/expected ratio (o/e) 1.19, 90% interval 1.03 to 1.37.
Homologues: Orthologues: chimpanzee DDAH1 (99% identical), rabbit DDAH1 (96% identical), dog DDAH1 (94% identical), mouse Ddah1 (94% identical), rat Ddah1 (93% identical), macaque DDAH1 (90% identical), guinea pig DDAH1 (81% identical), tropical clawed frog ddah1 (78% identical), pig DDAH1 (62% identical), zebrafish ddah1 (40% identical), Drosophila melanogaster CG1764 (38% identical), Caenorhabditis elegans T22B7.3 (22% identical), and 1 more. Paralogues in human: DDAH2 (51% identical).
Diseases named in the same sentence as DDAH1 in open-access papers:
DDAH1 is named in the same sentence as 123 diseases in open-access papers, as found by Europe PMC text mining. Sharing a sentence is not in itself a finding about the gene and the disease. The quoted sentences say what the papers report.
endothelial dysfunction (20 papers, 2009 to 2025). In vascular diseases, endothelial dysfunction is a systemic pathological state of the endothelium (the inner lining of blood vessels) and can be broadly defined as an imbalance between vasodilating and vasoconstricting substances produced by (or acting on) the endothelium. "A reduction in DDAH1 catalytic activity and/or expression is therefore a potential contributor to endothelial dysfunction and increased cardiovascular risk." (PMID 28588208, 2017). "Endothelial DDAH1 reduces this effect, and low levels of DDAH1 in RCAs may render them susceptible to endothelial dysfunction contributing to vasospasm, changes opposed by L-arginine." (PMID 38226470, 2024). "It was previously hypothesized that hyperglycemia causes endothelial dysfunction by down-regulating DDAH1 and this theory was supported by data from a rodent model of chronic hyperglycemia." (PMID 37005603, 2023). "DDAH1 promotes vascular injury repair and angiogenesis, whereas ADMA is strongly associated with endothelial dysfunction, hypertension, and ischemia-reperfusion injury." (PMID 35620579, 2022). "Dihydromyricetin attenuates TNF-α-induced endothelial dysfunction via miR-21-mediated DDAH1/ADMA/NO pathway, which further supports our findings." (PMID 36561848, 2022). "Taken together, these data demonstrated that miR-21-mediated DDAH1/ADMA/NO signal pathway plays an important role in TNF-α-induced endothelial dysfunction, and DMY attenuated endothelial dysfunction induced by TNF-α in a miR-21-dependent manner." (PMID 29682517, 2018). "Collectively, these results demonstrate that DMY attenuates TNF-α-induced endothelial dysfunction through mediating miR-21/DDAH1/ADMA cascade." (PMID 29682517, 2018). "In this study we demonstrate a further mechanism for hepatic ROS generation and sinusoidal endothelial dysfunction through decreased hepatocyte DDAH1 expression, leading to increased hepatic ADMA and eNOS dysfunction." (PMID 29263339, 2017). "Loss of DDAH-1 function in mice has been demonstrated to result in increased ADMA levels and endothelial dysfunction." (PMID 27431938, 2016). "In relation to this, it has been demonstrated that mice aorta and cerebral arterioles over-expressing DDAH-1 are protected against ADMA-induced endothelial dysfunction using 100 μM ADMA." (PMID 27431938, 2016). "Further, DDAH1-transgenic mice display a significant increase in NOS activity and a decreased risk of endothelial dysfunction compared to the wild type mice." (PMID 24465497, 2014). "One study showed that homozygous DDAH1-deficient mice die before birth while the heterozygous DDAH1-deficient mice have a 20% increased level of ADMA and develop severe endothelial dysfunction." (PMID 24465497, 2014). "Recent evidence suggests that DDAH-1 overexpression protects from endothelial dysfunction in cerebral arterioles." (PMID 19809508, 2009). "In DDAH1 KO-/+ animals, reduced NO production was linked to endothelial dysfunction, but without evaluation of potential immune effects." (PMID 34804992, 2021). "In addition 4-HNE can directly form an adduct with DDAH1, inhibiting DDAH1 activity and promoting endothelial dysfunction." (PMID 31345174, 2019). "Thus, the aim of present study is to investigate the attenuating effects of DMY on endothelial dysfunction through regulating miR-21 expression and its related DDAH1/ADMA/NO signal pathway." (PMID 29682517, 2018). "Thus, we hypothesize that DMY attenuates TNF-α-induced endothelial dysfunction through mediating miR-21/DDAH1/ADMA cascade, which in turn results in enhancing NO production." (PMID 29682517, 2018). "However, whether the deleterious effects of miR-21 on endothelial dysfunction are through mediating DDAH1/ADMA/NO signal pathway, especially under the inflammatory cytokine TNF-α, is still not unclear." (PMID 29682517, 2018).
endothelial dysfunction (continued). "This is in line with reports from DDAH1 knockout mice that are characterized by increased ADMA, impaired vascular NO release, endothelial dysfunction, and systemic and pulmonary arterial hypertension." (PMID 37330534, 2023). "We crossed AGXT2 TG mice with DDAH1 knockout mice and observed that upregulation of AGXT2 lowers plasma ADMA and pulse pressure and protects the mice from endothelial dysfunction and adverse aortic remodeling." (PMID 35672381, 2022). "DDAH1 transgenic mice have increased basal NO production in the aorta and are protected from ADMA-mediated endothelial dysfunction in cerebral arterioles." (PMID 31533264, 2019). "DDAH1 knockout mice have elevated plasma and tissue ADMA concentrations, endothelial dysfunction and hypertension." (PMID 31533264, 2019). "It inhibits miR-21 expression and then improves endothelial dysfunction induced by TNF-α, accompanied by suppression of abnormal expression of eNOS, DDAH1, NO, and ADMA, as well as improvement of tube formation and migration." (PMID 31178721, 2019). "To test this hypothesis we generated and characterized AGXT2 transgenic mice and determined, whether this transgene can protect Ddah1 knockout mice from ADMA elevation, endothelial dysfunction and aortic remodeling." (PMID 35672381, 2022). "In conclusion, the present study in HUVECs demonstrated that miR-21-mediated DDAH1/ADMA/NO signal pathway plays an important role in TNF-α-induced endothelial dysfunction, and DMY attenuated endothelial dysfunction induced by TNF-α in a miR-21-dependent manner." (PMID 29682517, 2018). "The absence of DDAH1 caused increased ADMA levels, which led to decreased eNOS and NO contents and increased generation of ROS, thereby leading to leukocyte transendothelial migration, oxidative stress, endothelial dysfunction, and EMT." (PMID 35620579, 2022). "Thus, it is likely that post-transcriptional regulation of DDAH1 mRNA is partially responsible for the decrease in DDAH1 protein expression seen in hepatocytes during times of oxidative stress, leading to increased ADMA and consequent endothelial dysfunction." (PMID 29263339, 2017). "Last but not least enhancement of DDAH-1 expression increases basal levels of vascular NO and protects against ADMA-induced endothelial dysfunction in the cerebral circulation." (PMID 23202900, 2012). "Additionally, improvement of endothelial dysfunction can be reversed by a non-specific NOS inhibitor, indicating DHM ameliorates vascular endothelial function and inhibits atherosclerosis by targeting miR-21-mediated DDAH1/ADMA/NO signal pathway." (PMID 31178721, 2019).
glioma (12 papers, 2002 to 2024). A benign or malignant brain and spinal cord tumor that arises from glial cells (astrocytes, oligodendrocytes, ependymal cells). "Together these studies suggest that, at least in C6 gliomas, the effect of DDAH1 on tumor growth and angiogenesis is purely NO-dependent." (PMID 31993367, 2019). "Studies to date have demonstrated an increase in DDAH1 protein expression in human glioma, meningioma, prostate cancer, and hepatocellular carcinoma, primarily by means of large-scale proteomic analysis." (PMID 31993367, 2019). "Glioma xenografts expressing an active-site mutant of DDAH1, incapable of metabolising ADMA, grew faster than DDAH1-null xenografts, but not as fast as those expressing WT DDAH150." (PMID 29070803, 2017). "Nitric oxide metabolism has been implicated in carcinogenesis, tumor progression, angiogenesis, and response to therapy; in particular, overexpression of DDAH1 resulted in increased tumor growth and vascularization in a model of glioma tumorigenesis." (PMID 24634783, 2014). "The presence of ADMA-independent effects of DDAH1 is also supported by the observation that overexpression of the active site mutant of DDAH1 was able to affect the growth of glioma xenografts, while the total DDAH activity in the lysates of tumor cells remained unchanged." (PMID 31533264, 2019). "Recent reports have demonstrated that overexpression of Ddah1 enhances the expression of NO and vascular endothelial growth factor (VEGF) to promote angiogenesis and the growth of glioma in vitro and in vivo." (PMID 33628783, 2021). "(2002) showed that DDAH1 did not influence glioma cell proliferation in vitro." (PMID 28580735, 2017).
pulmonary hypertension (11 papers, 2011 to 2023). Increased pressure within the pulmonary circulation due to lung or heart disorder. "A microarray analysis revealed upregulation of Arg1 and downregulation of Ddah1, molecules whose altered expression has previously been associated with pulmonary arterial hypertension." (PMID 24303100, 2013). "Downregulation or reduced activity of DDAH1 leads to apoptotic activation and reduced angiogenesis, and rs480414 SNP in DDAH1 was previously found to be protective against the development of pulmonary hypertension in BPD patients." (PMID 36757497, 2023). "Common single nucleotide polymorphisms in the DDAH1 and DDAH2 genes predispose humans to high ADMA levels and hypoxia-induced pulmonary arterial hypertension." (PMID 37629272, 2023). "Improvement in eNOS activity and higher DDAH1 protein expression levels were believed to have a positive effect on inflammation and oxidative stress in pulmonary hypertension." (PMID 35620579, 2022). "Recent genetic analyses performed in our laboratory revealed significant associations of single nucleotide polymorphisms (SNPs) in the NOS III, DDAH1, AGXT2, and ARG2 genes with high altitude pulmonary hypertension." (PMID 35252268, 2022). "Dimethylarginine Dimethyl AminoHydrolase 1 (DDAH1) is known to be involved in NO signalling in cardiovascular disease and pulmonary hypertension." (PMID 21347291, 2011). "We found four genes to be significantly associated with high-altitude pulmonary hypertension (i.e., estimated mPAP ≥ 30 mm Hg) after adjustment for multiple testing: NOS3 rs2070744 (p = 0.003), ARG2 rs3742879 (p = 0.003), DDAH1 rs233122 (p = 0.004), and AGXT2 rs37369 (p = 0.003)." (PMID 34945057, 2021). "Therefore, we selected 16 single nucleotide polymorphisms in NOS3, DDAH1, DDAH2, AGXT2, ARG1, ARG2, and PRMT1 genes and studied their associations with dimethylarginine concentrations and the incidence of high-altitude pulmonary hypertension as well as acclimatization to high altitude." (PMID 34945057, 2021). "Ddah1 knockout (KO) mice may therefore help to understand the pathophysiological roles of this enzyme and its substrate, ADMA, in the development of hypoxia-associated pulmonary hypertension." (PMID 33281630, 2020). "In the chronic hypoxia-induced pulmonary hypertension model, increased ADMA levels were observed along with reduced DDAH-1 expression and activity." (PMID 34356605, 2021). "On the other hand, exogenously added ADMA increased the stabilization of HIF-1α protein in HPAECs, further decreasing DDAH-1 expression and activating HIF-1α dependent pathways, resulting in the development of pulmonary hypertension phenotype." (PMID 34356605, 2021). "In WT mice, downregulation of DDAH1 may be the major cause for elevation of ADMA in hypoxia, while in Ddah1−/− mice, DDAH2 protein is upregulated, limiting further dysregulation of ADMA-related pathways and, by this, pulmonary hypertension and cardiac hypertrophy in hypoxia." (PMID 33281630, 2020). "By contrast, DDAH1 overexpression decreased acute hypoxic pulmonary vasoconstriction, but it did not change chronic hypoxia-induced pulmonary hypertension in mice." (PMID 33281630, 2020).
Hypertension (10 papers, 2012 to 2022). The presence of chronic increased pressure in the systemic arterial system. "Our results indicated that the C-allele of rs3087894 in DDAH1 was a risk factor for hypertension in the Kazakh group but a protective factor in the Uygur group." (PMID 26786611, 2016). "The main finding from this study was that it demonstrated that the C-allele of rs3087894 in DDAH1 is a risk factor for hypertension in the Kazakh group but a protective factor in the Uygur group." (PMID 26786611, 2016). "The G/C genotype of rs3087894 in DDAH1 was a risk factor for hypertension in the Kazakh group in the co-dominant model (G/C versus G/G) (OR 1.39; 95% CI: 1.02-1.88; P < 0.05), with the same result in the dominant model (G/C + C/C versus G/G) (OR 1.38; 95% CI: 1.03-1.84; P < 0.05)." (PMID 26786611, 2016). "Polymorphisms in the NOS3, DDAH1, DDAH2, and AGXT2 genes have previously been shown to relate to NO-mediated vascular function, hypertension, and mortality in a range of different patient populations." (PMID 34945057, 2021). "We conducted a case-control study on a Chinese population that included three ethnic groups (Han, Kazakh and Uygur), to systemically investigate associations between variations in the genes DDAH1 and DDAH2 and hypertension." (PMID 26786611, 2016). "In view of the genetic heterogeneity among ethnic groups, in the present study we aimed to systemically evaluate associations between the DDAH1 and DDAH2 variants and hypertension in three ethnic groups within the Chinese population (Han, Kazakh and Uygur)." (PMID 26786611, 2016). "For seven of overall 17 potential target genes, we found studies reporting a role in CVD, comprising HF and cardiac remodeling after MI (Ccnd2, Pde1c, Ddah1), atherosclerosis (Igf1r), blood pressure and hypertension (Fign, Efnb3), and type 2 diabetes (Igf2bp2)." (PMID 35332188, 2022). "In addition, the variants of two enzymes have been shown to be associated with several vascular conditions and diseases (AGXT2: carotid atherosclerosis, atrial fibrillation and ischemic stroke, and coronary heart disease; DDAH1: hypertension and T2DM)." (PMID 33879046, 2021). "DDAH1 transgenic mice were protected from renal injury in a murine model of hypertension." (PMID 31533264, 2019). "The lack of protection in cardiac and aortic tissues may be due to DDAH1 tissue selectivity and/or the extent of hypertension by the used combined model." (PMID 23110194, 2012). "The aim of the present study was to investigate the role of ADMA and its degrading enzyme DDAH1 in the development of hypertension-induced end organ damage (i.e. aortic, cardiac, and renal tissues) using the recently developed DOCA and Ang II-induced murine hypertension model." (PMID 23110194, 2012). "Missense variants of AGXT2, but not DDAH1, may be related to vulnerability to vascular diseases such as hypertension and DM via the NO system." (PMID 33879046, 2021). "Therefore, we investigated the role of ADMA and DDAH1 in hypertension-induced end organ damage using the uninephrectomized, deoxycorticosterone actetate salt, and angiotensin II-induced hypertension model in human DDAH1 (hDDAH1) overexpressing and wild-type (WT) mice." (PMID 23110194, 2012). "A large number of candidate genes for hypertension have now been widely studied and, among these, the genes DDAH1 and DDAH2 seem to have an influence on hypertension, since they play a fundamental role in maintaining endothelial function." (PMID 26786611, 2016). "Considering the results of our study and the work by others, overexpression of DDAH1 does not seem to play a significant role in the context of hypertension-induced cardiac end organ damage." (PMID 23110194, 2012).
Hypertension (continued). "Apart from the associations of the genetic models of the eNOS knockout mice and the DDAH1 transgenic mice with insulin sensitivity noted earlier, it has been shown that infusion of the NOS-inhibitor N-monomethyl L-arginine (L-NMMA) in rats induced hypertension and insulin-resistance." (PMID 34492019, 2021). "The increased systemic hypertension observed in DDAH1 KO mice in which ADMA levels were increased and NO production was decreased suggests that DDAH1 degradation of ADMA is physiologically important and may help protect against cardiovascular diseases in which ADMA levels are elevated." (PMID 23878601, 2013).